GSK3B (glycogen synthase kinase 3 beta)
Description:
Constitutively active protein kinase that acts as a negative regulator in the hormonal control of glucose homeostasis, Wnt signaling and regulation of transcription factors and microtubules, by phosphorylating and inactivating glycogen synthase (GYS1 or GYS2), EIF2B, CTNNB1/beta-catenin, APC, AXIN1, DPYSL2/CRMP2, JUN, NFATC1/NFATC, MAPT/TAU and MACF1. Requires primed phosphorylation of the majority of its substrates. In skeletal muscle, contributes to insulin regulation of glycogen synthesis by phosphorylating and inhibiting GYS1 activity and hence glycogen synthesis. May also mediate the development of insulin resistance by regulating activation of transcription factors. Regulates protein synthesis by controlling the activity of initiation factor 2B (EIF2BE/EIF2B5) in the same manner as glycogen synthase. In Wnt signaling, GSK3B forms a multimeric complex with APC, AXIN1 and CTNNB1/beta-catenin and phosphorylates the N-terminus of CTNNB1 leading to its degradation mediated by ubiquitin/proteasomes. Phosphorylates JUN at sites proximal to its DNA-binding domain, thereby reducing its affinity for DNA. Phosphorylates NFATC1/NFATC on conserved serine residues promoting NFATC1/NFATC nuclear export, shutting off NFATC1/NFATC gene regulation, and thereby opposing the action of calcineurin. Phosphorylates MAPT/TAU on 'Thr-548', decreasing significantly MAPT/TAU ability to bind and stabilize microtubules. MAPT/TAU is the principal component of neurofibrillary tangles in Alzheimer disease. Plays an important role in ERBB2-dependent stabilization of microtubules at the cell cortex. Phosphorylates MACF1, inhibiting its binding to microtubules which is critical for its role in bulge stem cell migration and skin wound repair (By similarity). Probably regulates NF-kappa-B (NFKB1) at the transcriptional level and is required for the NF-kappa-B-mediated anti-apoptotic response to TNF (TNF/TNFA) (By similarity). Negatively regulates replication in pancreatic beta-cells, resulting in apoptosis, loss of beta-cells and diabetes (By similarity). Through phosphorylation of the anti-apoptotic protein MCL1, may control cell apoptosis in response to growth factors deprivation (By similarity). Phosphorylates MUC1 in breast cancer cells, decreasing the interaction of MUC1 with CTNNB1/beta-catenin. Is necessary for the establishment of neuronal polarity and axon outgrowth. Phosphorylates MARK2, leading to inhibition of its activity (By similarity). Phosphorylates SIK1 at 'Thr-182', leading to sustainment of its activity. Phosphorylates ZC3HAV1 which enhances its antiviral activity. Phosphorylates SNAI1, leading to its ubiquitination and proteasomal degradation. Phosphorylates SFPQ at 'Thr-687' upon T-cell activation. Phosphorylates NR1D1 st 'Ser-55' and 'Ser-59' and stabilizes it by protecting it from proteasomal degradation. Regulates the circadian clock via phosphorylation of the major clock components including BMAL1, CLOCK and PER2. Phosphorylates FBXL2 at 'Thr-404' and primes it for ubiquitination by the SCF(FBXO3) complex and proteasomal degradation (By similarity). Phosphorylates CLOCK AT 'Ser-427' and targets it for proteasomal degradation. Phosphorylates BMAL1 at 'Ser-17' and 'Ser-21' and primes it for ubiquitination and proteasomal degradation. Phosphorylates OGT at 'Ser-3' or 'Ser-4' which positively regulates its activity. Phosphorylates MYCN in neuroblastoma cells which may promote its degradation. Regulates the circadian rhythmicity of hippocampal long-term potentiation and BMAL1 and PER2 expression (By similarity). Acts as a regulator of autophagy by mediating phosphorylation of KAT5/TIP60 under starvation conditions, activating KAT5/TIP60 acetyltransferase activity and promoting acetylation of key autophagy regulators, such as ULK1 and RUBCNL/Pacer. Negatively regulates extrinsic apoptotic signaling pathway via death domain receptors. Promotes the formation of an anti-apoptotic complex, made of DDX3X, BRIC2 and GSK3B, at death receptors, including TNFRSF10B. The anti-apoptotic function is most effective with weak apoptotic signals and can be overcome by stronger stimulation. Phosphorylates E2F1, promoting the interaction between E2F1 and USP11, stabilizing E2F1 and promoting its activity. Phosphorylates mTORC2 complex component RICTOR at 'Ser-1235' in response to endoplasmic stress, inhibiting mTORC2. Phosphorylates mTORC2 complex component RICTOR at 'Thr-1695' which facilitates FBXW7-mediated ubiquitination and subsequent degradation of RICTOR. Acts as a negative regulator of smoothened signaling by mediating phosphorylation of GLI2 and GLI3 in absence of smoothened, promoting their processing by the SCF(BTRC) complex. Phosphorylates FXR1, promoting FXR1 ubiquitination by the SCF(FBXO4) complex and FXR1 degradation by the proteasome (By similarity). Phosphorylates interleukin-22 receptor subunit IL22RA1, preventing its proteasomal degradation (By similarity). Phosphorylates and inhibits the CTP synthase and protein-asparagine deamidase activities of CTPS1. Phosphorylates DSP at multiple sequential serine residues in the C-terminus tail, promoting its recruitment to developing desmosome cell-cell junctions.
Tractability: Small molecule: an approved drug acts on it; a structure with a bound ligand is known; a high-quality ligand is known; it has a high-quality binding pocket; it belongs to a druggable protein family. Antibody: UniProt places it where antibodies can reach, with high confidence; its Gene Ontology location is reachable by antibodies, with high confidence. PROTAC: it is named in the literature on targeted protein degradation; ubiquitination databases record sites on it; its protein half-life has been measured; a small molecule that binds it is known.
Target class: Protein Kinase; CMGC protein kinase group; Enzyme; Kinase; CMGC protein kinase GSK family
Chemical probes: AZ2858 (high quality), BI-5521 (high quality), CHIR-99021 (high quality), Indirubin-3'-monoxime, LY-2090314 (high quality), ML320, PD081291, PD081329, PD081771, PD082474, PD082881, PD083514, PD083980, PF-367 (high quality), PQ-1, PT-65, SB-216763 (high quality), SGC-CDKL5/GSK3-1 (high quality), SGC-GSK3-1 (high quality), Tideglusib
Safety:
Unwanted effects reported when the protein is acted on. In parentheses: how it was acted on, where the effect was seen, and who reports it.
abnormal bone development (inhibition; bone; source: Brennan et al. (2024))
Carcinogenicity (inhibition; source: Brennan et al. (2024))
cardiac dysfunction (inhibition; cardiovascular; source: Brennan et al. (2024))
female infertility (inhibition; reproductive; source: Brennan et al. (2024))
insulin resistance (inhibition; source: Brennan et al. (2024))
male infertility (inhibition; reproductive; source: Brennan et al. (2024))
Mitochondrial toxicity (activation; source: Brennan et al. (2024))
motor dysfunction (inhibition; source: Brennan et al. (2024))
myocardial fibrosis (activation; cardiovascular; source: Brennan et al. (2024))
neurotoxicity (inhibition; central nervous system; source: Brennan et al. (2024))
renal failure (inhibition; renal; source: Brennan et al. (2024))
tissue hyperplasia (inhibition; source: Brennan et al. (2024))
heart disease (cardiovascular system; source: Force et al. (2011))
Gene: Protein-coding gene on chromosome 3 (119,821,321 to 120,094,994, reverse strand). Ensembl gene ENSG00000082701.
Subcellular location: Cytoplasm; Nucleus; Cell membrane
Subcellular location (Human Protein Atlas): Nucleoplasm
Pathways (Reactome):
Disease: APC truncation mutants have impaired AXIN binding; AXIN missense mutants destabilize the destruction complex; CTNNB1 S33 mutants aren't phosphorylated; CTNNB1 S37 mutants aren't phosphorylated; CTNNB1 S45 mutants aren't phosphorylated; CTNNB1 T41 mutants aren't phosphorylated; Constitutive Signaling by AKT1 E17K in Cancer; Maturation of nucleoprotein; Signaling by GSK3beta mutants; Truncations of AMER1 destabilize the destruction complex
Signal Transduction: AKT phosphorylates targets in the cytosol; Beta-catenin phosphorylation cascade; Degradation of GLI2 by the proteasome; Degradation of beta-catenin by the destruction complex; Disassembly of the destruction complex and recruitment of AXIN to the membrane; GLI3 is processed to GLI3R by the proteasome
Cell Cycle: Ubiquitin-Mediated Degradation of Phosphorylated Cdc25A; Ubiquitin-dependent degradation of Cyclin D
Cellular responses to stimuli: GSK3B and BTRC:CUL1-mediated-degradation of NFE2L2; Regulation of HSF1-mediated heat shock response
Developmental Biology: CRMPs in Sema3A signaling; Transcriptional and post-translational regulation of MITF-M expression and activity
Gene expression (Transcription): B-WICH complex positively regulates rRNA expression; Regulation of RUNX2 expression and activity
Immune System: GSK3B-mediated proteasomal degradation of PD-L1(CD274)
Gene Ontology:
Molecular function: beta-catenin binding; dynactin binding; kinase activity; NF-kappaB binding; protease binding; protein binding; protein kinase A catalytic subunit binding; protein kinase activity; protein kinase binding; protein serine kinase activity; protein serine/threonine kinase activity; RNA polymerase II-specific DNA-binding transcription factor binding; scaffold protein binding; tau-protein kinase activity; ubiquitin protein ligase binding; tau protein binding; ATP binding; dynein complex binding
Biological process: canonical Wnt signaling pathway; cellular response to retinoic acid; epithelial to mesenchymal transition; ER overload response; glycogen metabolic process; hippocampus development; intracellular signal transduction; mitochondrion organization; negative regulation of apoptotic process; negative regulation of calcineurin-NFAT signaling cascade; negative regulation of canonical Wnt signaling pathway; negative regulation of cell migration; negative regulation of epithelial to mesenchymal transition; negative regulation of extrinsic apoptotic signaling pathway via death domain receptors; negative regulation of gene expression; negative regulation of mesenchymal stem cell differentiation; negative regulation of osteoblast differentiation; negative regulation of protein-containing complex assembly; negative regulation of smoothened signaling pathway; negative regulation of TORC2 signaling; neuron projection development; peptidyl-serine phosphorylation; positive regulation of cell differentiation; positive regulation of cell-matrix adhesion; positive regulation of gene expression; and 62 more
Cellular component: beta-catenin destruction complex; centrosome; cytoplasm; glutamatergic synapse; nucleoplasm; nucleus; plasma membrane; axon; cytosol; dendrite; endoplasmic reticulum lumen; Wnt signalosome; cell body; dendritic shaft; growth cone; meiotic spindle; neuronal cell body; perinuclear region of cytoplasm; postsynaptic density; presynapse; ribonucleoprotein complex
Genetic constraint (gnomAD): Loss-of-function variants: 0 observed, 5.84 expected, observed/expected ratio (o/e) 0, 90% interval 0 to 0.51. That is too few expected variants to judge how well the gene tolerates losing a copy. Missense variants: 66 observed, 101.58 expected, observed/expected ratio (o/e) 0.65, 90% interval 0.53 to 0.8. Synonymous variants: 37 observed, 40.4 expected, observed/expected ratio (o/e) 0.92, 90% interval 0.7 to 1.21.
Homologues: Orthologues: macaque GSK3B (100% identical), rabbit GSK3B (99% identical), mouse Gsk3b (99% identical), pig GSK3B (99% identical), rat Gsk3b (99% identical), guinea pig GSK3B (99% identical), chimpanzee GSK3B (96% identical), zebrafish gsk3ba (95% identical), tropical clawed frog gsk3b (91% identical), zebrafish gsk3bb (89% identical), Drosophila melanogaster sgg (76% identical), dog GSK3B (72% identical), and 2 more. Paralogues in human: GSK3A (77% identical).
Diseases named in the same sentence as GSK3B in open-access papers:
GSK3B is named in the same sentence as 594 diseases in open-access papers, as found by Europe PMC text mining. Sharing a sentence is not in itself a finding about the gene and the disease. The quoted sentences say what the papers report.
breast cancer (386 papers, 2003 to 2026). A primary or metastatic malignant neoplasm involving the breast. "In BRCA1 gene-deficient breast cancer, PARPi also upregulates PD-L1 expression on tumor cell surfaces by inactivating GSK3β, thereby inhibiting the activation of tumor-infiltrating T lymphocytes." (PMID 38762484, 2024). "AKT-regulated GSK3β activity was associated with growth in breast cancer and migration in gastric cancer cells." (PMID 39337655, 2024). "While more studies are needed to fully clarify the mechanism underlying EDI3’s regulation via GSK3β and mTORC1, these initial results present potential regulatory candidates that are themselves deregulated in breast cancer." (PMID 36670508, 2023). "The serine 9 phosphorylation of GSK3β is negatively correlated with the activity of GSK3β, which is adversely associated with the viability of breast cancer cells." (PMID 36900408, 2023). "In breast cancer cells, overexpression of GSK3β indicates poor prognosis and increases the risk of relapse." (PMID 37259304, 2023). "Meanwhile, the expression abundance of Notch3 and GSK3β was associated with different breast cancer subtypes, and significantly increased in luminal breast cancer type compared with other subtypes (p = 0.037)." (PMID 36139447, 2022). "To further investigate the association of Notch3 and GSK3β in breast cancer, we evaluated the protein and mRNA expression levels of GSK3β in MCF-7 and MDA-MB-231 cell lines with high and low expression of Notch3." (PMID 36139447, 2022). "Immunohistochemistry of Notch3 and GSK3β in breast cancer specimens revealed that Notch3 and GSK3β expression are positively associated (r = 0.416, p = 0.001)." (PMID 36139447, 2022). "In human breast cancer, overexpression of GSK-3β is associated with poor prognosis indicators (increased tumor size, ER-negative disease, high pathological grade, PR-negative disease, and relapse after tumor resection)." (PMID 32283796, 2020). "Our experimental results showed that GSK3B was also highly expressed in breast cancer tissues and was associated with poor survival, as was β-catenin." (PMID 30181805, 2018). "In conclusion, TPA-induced migration of MCF-7 breast cancer cells is associated with the up-regulation of fascin-1 gene transcription, which is mediated through the activation of the PKCδ/STAT3α, PKCδ/GSK3β/β-catenin, and Wnt-1/β-catenin signaling pathways." (PMID 27036017, 2016). "SLC39A6 was linked to MET in breast cancer through SLC39A6-induced zinc influx when N-terminal cleavage inactivates GSK-3β; as a result, unphosphorylated Snail in the nucleus downregulates the adherence genes, such as E-cadherin." (PMID 26444413, 2015). "Third, we also demonstrated that APP is mechanistically linked to the AKT/FOXO and AKT/GSK3-β pathways which are known to modulate cell growth, survival, and invasion of breast cancer cells through the regulation of target genes including p27kip1 and survivin." (PMID 25491510, 2014). "The exposure to light at night was found to suppress the nocturnal pineal gland melatonin synthesis leading to the inhibition of circadian phosphorylation of GSK3β and hence increasing the susceptibility to breast cancer spread." (PMID 24319459, 2013). "This is in contrast to the recent report that TNFα stabilized Snail through NF-κB-dependent induction of CSN2 in breast cancer cells, which inhibited the association of Snail with GSK3β and thus suppressed its phosphorylation and degradation." (PMID 20661477, 2010). "To test whether these are clinically relevant factors in basal-like breast cancer, we show that high expression of HSP27 and GSK-3β is associated with poor survival of basal-like breast cancer patients." (PMID 41279138, 2025).
breast cancer (continued). "Moreover, GSK3β-mediated CPD phosphorylation of FBXW7 is critical for breast cancer proliferation-associated substrate recruitment." (PMID 37658431, 2023). "Finally, over-expression of both Notch3 and GSK3β mRNA was found to be associated with better recurrence-free survival (RFS) in all patients with breast cancer." (PMID 36139447, 2022). "In human breast cancer samples, Notch3 expression is positively associated with GSK3β (r = 0.416, p = 0.001); moreover, high expressions of Notch3 and GSK3β mRNA are correlated to better relapse-free survival in all breast cancer patients via analysis in “the Kaplan–Meier plotter” database." (PMID 36139447, 2022). "Interestingly, a recent study demonstrated that loss of CAR in breast cancer cells leads to hyperactivation of Akt and GSK3-β kinases leading to TGF-β1-induced epithelial to mesenchymal transition." (PMID 36302767, 2022). "Furthermore, our experimental results showed that GSK3B was also highly expressed in breast cancer tissues and associated with poor survival." (PMID 30181805, 2018). "Furthermore, this regulation suppressed EZH2 oncogenic functions and EZH2 enzymatic activity (trimethylation of H3K27) is inversely associated with GSK3β activity in tumor tissues from human breast cancer patients." (PMID 27494834, 2016). "Furthermore, we proved that these metastatic behavior promoting effects of RNF8 in breast cancer was associated with the inactivation of GSK-3β and activation of β-catenin signaling." (PMID 27259701, 2016). "Our findings that APP is functionally linked with AKT activation and GSK-3β/β-catenin pathways warrant the future study that elevated APP in malignant breast cancers is associated with dissemination of breast cancer into other target organs by promoting EMT process." (PMID 25491510, 2014). "Moreover, another important finding in the current study was the suppression of GSK3β activity underlying the mechanism whereby Aur-A activated mTOR signaling in breast cancer cells." (PMID 25115395, 2014). "In addition, Notch3 and GSK3β expression was positively associated in human breast cancer samples." (PMID 36139447, 2022). "This point requires additional validation if USP10 or GSK3β inhibitors are to be used in the treatment of PI3K-mutant breast cancers." (PMID 40991650, 2025). "For instance, it has been reported that GSK-3β expression is markedly reduced in breast cancer tissues relative to normal tissues." (PMID 40656954, 2025). "Epidermal growth factor (EGF) stabilizes PD-L1 through GSK3b inactivation in basal-like breast cancer." (PMID 39958358, 2025). "GSK3-β inhibitors were found to suppress the growth of breast cancer cells and to sensitize breast cancer cells to irinotecan, a chemotherapeutic agent." (PMID 41009395, 2025). "In our study, SGK3 was demonstrated to be responsible for the resistance to BYL719 and enhanced breast cancer stemness by increasing the phosphorylation levels of GSK3β and β-catenin." (PMID 40303291, 2025). "Here we found that CLDN6 promotes the NRF2 nuclear export to induce ferroptosis by the AKT/GSK3β/FYN axis in breast cancer cells." (PMID 39984471, 2025). "The second described mechanism is based on the concept that inactivating GSK3β has been shown to stabilize and increase PD‐L1 in breast cancer cells." (PMID 39258533, 2025). "Meanwhile, the epidermal growth factor (EGF) stabilizes PD-L1 through GSK3b inactivation in basal-like breast cancer." (PMID 39958358, 2025). "miR-3646 has been reported to act as a potential oncogene in lung adenocarcinoma and breast cancer and to contribute to docetaxel resistance in breast cancer cells by suppressing the GSK-3β/β-catenin signaling pathway." (PMID 41614739, 2025). "We also confirmed that in breast cancer cell type, the Akt/GSK-3β signalling pathway is activated by solid stress compression." (PMID 40371393, 2025).